CD40LG (CD40 ligand)
Diseases named in the same sentence as CD40LG in open-access papers (continued):
Sharing a sentence is not in itself a finding about the gene and the disease.
invasive breast carcinoma (2 papers, 2020 to 2021). A carcinoma that infiltrates the breast parenchyma. "On the other hand, it has been shown that CD40 is significantly correlated with CD40LG gene expression in 529 patients with invasive carcinoma of the breast according to the TCGA (Provisional) data set of the Agilent microarray platform (Pearson correlation: 0.53, P < 0.05)." (PMID 32256143, 2020).
Obstructive Sleep Apnea (2 papers, 2021 to 2023). "CD40LG and GZMB might play a vital role in the visceral adipose tissue homeostasis of obstructive sleep apnea patients." (PMID 36923793, 2023).
proliferative diabetic retinopathy (2 papers, 2016 to 2023). Advanced retinopathy due to diabetes mellitus characterized by the formation of new vessels in the retina. "We aimed to investigate the role of the CD40-CD40 ligand (CD40L) pathway in inflammation-mediated angiogenesis in proliferative diabetic retinopathy (PDR)." (PMID 37958563, 2023).
thyroid cancer (2 papers, 2021 to 2022). "Subsequently, the TCGA database results showed the expression of CXCL10, CD40LG, KRT14, TRAT1, and TREM2, with only TREM2 expression levels being upregulated in thyroid cancer (P < 0.05)." (PMID 36438899, 2022). "Subsequently, TCGA database results showed the expression of CXCL10, CD40LG, KRT14, TRAT1, and TREM2, with only TREM2 expression levels being upregulated in thyroid cancer." (PMID 36438899, 2022). "Overall, we observed significant association between IGSF10 and immune checkpoint genes such as CD200R1, VSIR, CD160, CD28, BTLA, and CD40LG in several tumors including low-grade glioma (LGG) and thyroid carcinoma (THCA)." (PMID 34351868, 2021).
X-linked lymphoproliferative syndrome (2 papers, 2023 to 2025). X-linked lymphoproliferative disease is a hereditary immunodeficiency characterized, in the majority of cases, by an inadequate immune response to infection with the Epstein-Barr virus (EBV). "Other IEIs such as X-linked Hyper IgM syndrome (XHIM) and X-linked lymphoproliferative syndrome (XLP1) caused by pathogenic variants of CD40LG or SH2D1A, can occasionally present with antibody deficiency." (PMID 41324804, 2025).
amoebiasis (1 paper, 2021). "Multiple pathways were potentially regulated by several hub genes; for example, ICOS, HLA − A, and CD40LG were related to regulate allograft rejection and cell adhesion molecules; IL10 was related to regulate allograft rejection, amoebiasis, and hematopoietic cell lineage." (PMID 34603484, 2021).
B-cell lymphoblastic leukemia (1 paper, 2022). "In childhood B-cell lymphoblastic leukemia cells, pre-B cells expressed CCR7 and migrated to CCL19, suggesting that CCR7 plays an important role in pre-B-cell lymphoblastic leukemia chemotaxis, whereas pro-B cells required the presence of the CD40 ligand to be CCL19/CCR7 responsive." (PMID 35203305, 2022).
hyperhomocysteinemia (1 paper, 2017). A serious metabolic condition caused by mutations in the MTHFR gene, medications, or nutritional deficiency. "Our recent evidence is shown that metabolic RF, such as uremic toxin or hyperhomocysteinemia, induced immune checkpoint molecule CD40 expression in monocytes (MC) and elevated serum soluble CD40 ligand (sCD40L) resulting in CD40+ MC differentiation." (PMID 28738836, 2017).
overactive bladder (1 paper, 2016). Symptom of overactive detrusor muscle of the urinary bladder that contracts with abnormally high frequency and urgency. "Other cytokines were also high in the urine of overactive bladder patients, including monocyte chemotactic protein-1 (MCP-1) and the soluble fraction of the CD40 ligand (scd40L)." (PMID 27176184, 2016).
peripheral arterial occlusion disease (1 paper, 2013). "In clinical studies, cilostazol treatment decreased P2Y12 reactivity index as a marker of platelet function, also decreased hsCRP and soluble CD40 ligand levels, and increased adiponectin level in diabetic patients with peripheral arterial occlusion disease." (PMID 23886346, 2013).
pulmonary alveolar proteinosis (1 paper, 2023). A rare lung disorder characterized by the filling of the pulmonary alveoli with proteinaceous material which stains positive with periodic acid-Schiff stain. "In addition, four previously reported patients with CD40LG mutation with pulmonary alveolar proteinosis were also analyzed." (PMID 37173671, 2023).
infection (4,444 papers, 2002 to 2026). The state of being infected such as from the introduction of a foreign agent such as serum, vaccine, antigenic substance or organism. "We also included combinations of stimuli to mimic bacterial response to infection (smooth lipopolysaccharide/sLPS, Pam3CSK4/P3C, CD40 ligand + IFNγ + sLPS/CIL, interleukin-10 + sLPS/LIL10)." (PMID 40866338, 2025). "The dynamics and interaction between CD4+CD25+ and co-stimulatory molecules such as CD28, CD80, CD40 and CD40LG during infection with A. phagocytophilum in sheep needs further investigation in the future." (PMID 37989861, 2023). "The CD40 and CD40 ligand interaction is known to regulate a wide range of immunological events, including infection-induced inflammatory response, CD8 T cell senescence and increased viral replication." (PMID 36532041, 2022). "The CD40-CD40 ligand expression and interaction are important not only for the activation of adaptive immune response, but also infection induced inflammation and CD8+ T cell apoptosis." (PMID 36532041, 2022). "During early Plasmodium berghei XAT (PbXAT) infection stage, expanding Vγ1+γδ T cells promotes CD40 ligand expression and IFN-γ secretion." (PMID 30116753, 2018). "For instance, female T cells can express more CD40LG or CXCR3, both of which are X-linked, and are generally more responsive to activation, produce more effector molecules like IFNγ in response to infection, and generate more short-lived effector cells than male-derived T cells." (PMID 40143355, 2025). "Infection was associated with the upregulation of proinflammatory genes CXCL10, IFNG, and IL15, alongside several NK and T cell activation markers such as CD244, CD40LG, and CD226." (PMID 39774119, 2025). "Afterwards, DCs can be activated by unconventional T cells by means of CD40 ligand expression, and whereafter, helper T lymphocyte 1 cells exert their effector response defending against Plasmodium via Th1 differentiation during PbXAT infection." (PMID 30116753, 2018). "The initial studies used CD40 ligand (CD40L) stimulation of B cells to make them receptive to infection, while others have cocultured B lymphocytes with virus producer cells to allow direct cell-to-cell virus transfer or have exposed B lymphocytes to concentrated preparations of KSHV (9, –, 12)." (PMID 26819313, 2016). "We observed higher expression of CD38, CD69 and CD40LG during active COVID-19 infection, indicating an activated phase of T cell population, compared to the healthy and the recovered, where the T cells are at resting phase in comparison to the active infection." (PMID 36532041, 2022). "Molecular studies for cryptosporidium infection, involving polymerase chain reaction amplication of parasite DNA in patients with CD40 ligand deficiency suggest that subclinical infection is common and in many cases the organism is not detectable by stool microscopy, but only by molecular testing." (PMID 20180797, 2010). "Our scRNA-seq showed the expression of Cd40lg in ILC3 clusters, likely induced due to ongoing infection." (PMID 38407132, 2024). "Both cell mediated and humoral responses to pathogen infection are dependent upon the co-stimulatory signal resulting from T cell CD40 ligand (CD40L, CD154) ligation with CD40 on antigen presenting cells." (PMID 35111692, 2021). "Cluster 3, which identified genes upregulated at day 7 post-infection, was highly enriched for T cell responsive genes, including those involved in T cell activation, lymphocyte proliferation, and TCR signaling, e.g. CD3D/E/G, CD8A/B, CD28, CD40LG, and GATA3." (PMID 38950078, 2024). "In addition, the activation-dependent expression of the platelet CD40 ligand contributes to the expansion phase of the virus-specific CD8+ T-cells, resulting in their accumulation at sites of infection." (PMID 33178607, 2020). "Moreover there is a group of molecules, including LTA, LTB, IL21, IFNAR2, CXCR3, IL17F and CD40LG, whose expression increased over the course of USA300 infection." (PMID 25719526, 2015).
infection (continued). "During infection or antigen immunization, antigen-experienced B cells migrate to the border between the T-cell zone and the B-cell follicle, where they are fully activated by interacting with T cells that express CD40 ligand (CD40L) and other co-stimulatory molecules." (PMID 40395311, 2023). "Other studies have indicated that epidermal growth factor (EGF), macrophage inflammatory protein (MIP)-1β, IL-1α, transforming growth factor (TGF)-α, soluble CD40 ligand (sCD40L), vascular endothelial growth factor (VEGF), IP-10, TNF-α, IL-12(p40), might discriminate between active TB and infection." (PMID 23691173, 2013).
tumor (896 papers, 1973 to 2026). "We also observed that AVPR2 was associated with the majority of tumour-infiltrating immune cell markers and immune-related genes, and that the expression of CD40LG, which plays a key role in B-cell activation, was positively correlated with AVPR2." (PMID 36998036, 2023). "The results showed CRCs harboring CSF1R c.1085 A>G variant had higher CD40LG and IL-2 expression in tumor tissues than those with CSF1R c.1085 genotype A_A." (PMID 34830445, 2021). "Neural stem cells derived from induced pluripotent stem cells transduced with baculovirus encoding CD40 ligand sufficiently inhibited tumor development in a preclinical model." (PMID 27494901, 2016). "CGTG-401 additionally contains the chimeric fiber from serotypes 5 and 3 for enhanced tumor transduction and encodes the human CD40 ligand." (PMID 28536390, 2016). "In this regard, the soluble form of CD40 ligand (sCD40L), whose serum concentrations have demonstrated prognostic value in PC patients, has been implicated in inflammation, angiogenesis, and immune suppression, among other tumor processes, via its CD40 receptor." (PMID 29662668, 2018). "CD40LG, an important immune molecule, has emerged as a crucial factor in modulating the tumor immune environment and affecting the outcomes of immunotherapy." (PMID 41048996, 2025). "Previous research has suggested that CD40LG has the potential to augment the effectiveness of immunotherapy by altering the immune microenvironment in a manner conducive to eliciting anti-tumor reactions 4-7." (PMID 41048996, 2025). "Recently, CD40LG has garnered significant attention within the oncology realm owing to its implication in shaping the tumor microenvironment." (PMID 41048996, 2025). "This indicates that CD40LG not only modulates the immune microenvironment but also directly influences tumor cell behavior." (PMID 41048996, 2025). "The findings consistently demonstrate that individuals exhibiting elevated CD40LG expression within tumor tissues exhibited significantly improved prognoses in terms of both OS (HR=0.57, P <0.0001) and PFS (HR=0.46, P<0.0001)." (PMID 41048996, 2025). "The correlation between CD40LG expression, immune cell infiltration, and clinical outcomes emphasizes its importance in tumor-immune dynamics and the efficacy of immunotherapy." (PMID 41048996, 2025). "Compared to the GB control, coculture conditions decreased the secretion of GRO‐alpha, a tumor‐supportive factor, and increased the secretion of the antitumor factors CD40 ligand and CD30." (PMID 40277152, 2025). "Soluble CD40 ligand (sCD40L) has shown promise as a potential biomarker in cancer diagnosis and progression, reflecting interactions between immune cells and the tumor microenvironment." (PMID 39120299, 2024). "In the TCGA BRCA dataset, similarly, the authors have demonstrated significant associations between lower expression of IFNG, CD40LG, and CXCR5 and larger tumor sizes or adjacent tissue invasion (p = 0.01, p = 0.03, and p = 0.01, respectively)." (PMID 39001456, 2024). "Consistently, we found significant associations between lower expression of IFNG, CD40LG, and CXCR5 and larger tumor sizes or adjacent tissue invasion (p = 0.01, p = 0.03 and p = 0.01, respectively)." (PMID 38831317, 2024). "DCs exposed to A. vulgaris extract, begin to express significantly more MHC II, costimulatory CD86 molecules systemically and express more CD40 ligand locally, thus becoming competent to correctly display tumor antigens and activate the T cell response." (PMID 38920557, 2024). "Expression levels of CD40LG and IL2RG presented borderline significant association values with tumor size." (PMID 38831317, 2024). "Stimulating immune receptors’ TNFRSF25 can enhance the eradication of tumor cells by T cells, and CD40LG activates immune cells and enhances inflammatory responses." (PMID 39062659, 2024).
tumor (continued). "One of these mRNA LNPs encoded CD40 ligand, which elicited potent ICD in tumor tissues, resulting in the expression of TAAs and CD40 ligand on the surface of tumor cells." (PMID 39543114, 2024). "Blockade of CD28 or CD40LG, including but not limited to genetic or pharmacologic means, mAbs and chimeric antigen receptor-based therapy, will suppress tumor growth and BM infiltration, thereby offering a novel therapeutic approach for the treatment of T-ALL." (PMID 38233409, 2024). "Both CD40 specific agonist antibody and recombinant soluble CD40 Ligand (CD40L) protein can effectively activate anti-tumor immune response in pre-clinical animal models." (PMID 39306655, 2024). "The other LNPs carried CD40 mRNA with the aim to be internalized by DCs for generating in situ engineered DCs, leading to increased expression of CD40 protein and activation upon interaction with CD40 ligand on tumor cells." (PMID 39543114, 2024). "CAR-T cells expressing CD40 ligand (CD40L) can not only directly enhance the killing of CD40-positive tumor cells but also activate APCs and mobilize other endogenous immune cells to participate in anti-tumor responses and avoid tumor immune escape." (PMID 37596653, 2023). "CD40LG, with the highest expression in C1, potentially induces an immune response to kill tumor cells by recruiting and activating the enhanced immune effectors to overcome immune escape." (PMID 36622242, 2023). "In MCL, overexpression of CD40L (CD40 ligand) in the tumor microenvironment mediates abnormal NF-κB activity promoting tumor cell survival." (PMID 37566089, 2023). "In the meantime, Th2 cells express IL-4, IL-5, IL-6, and IL-10 and support tumor cell growth through CD40–CD40 ligand (CD40L) interactions in HL and Helicobacter-induced MALT lymphomagenesis." (PMID 35326620, 2022). "Extensive studies have been conducted to investigate the underlying mechanism by which CD40LG and CD27 modulate tumor immunity." (PMID 36061181, 2022). "Co-stimulatory ICMs CD28, CD80 and CD40LG are secondary signal molecules in the T lymphocyte activation, which activate patients’ anti-tumor immune responses, leading to increased efficacy of cancer immunotherapy." (PMID 35953696, 2022). "Researchers have reported that CD40LG has a potent anti-tumor effect, which can be attributed to the CD40L–CD40LG interactions and can induce anti-tumor immunity by eliminating tumor-specific CD4+ and CD8+ tolerance." (PMID 36276933, 2022). "We demonstrated that P4HA1 expression was positively correlated with the expression of TNFSF15, CD80, VTCN1, TNFSF18, and CD200R1 in multiple tumor types but negatively correlated with the expression of CD40LG and CD244." (PMID 35812752, 2022). "This cytotoxicity is mediated by the CD40/CD40 ligand axis, as CD40 ligand on DCs can interact with CD40 on tumor cells." (PMID 35715855, 2022). "Correspondingly, co-administration of adenovirus encoding a chimeric, membrane-bound CD40 ligand (ISF35) with PD-1 and CTLA-4 inhibitors caused complete removing of injected tumor cells in the melanoma murine model." (PMID 34980128, 2022). "Combined single-cell RNA and T cell receptor sequencing showed that tumour-infiltrating CD40LG+ and CXCL13+ T helper cell clusters in a patient with pseudoprogression were dominated by a single IDH1(R132H)-reactive T cell receptor." (PMID 33762734, 2021). "We have shown a close correlation of the CD40/CD40LG axis with type-I anti-tumor T-cell responses in cancer." (PMID 34758832, 2021). "In general, Th2 cells tend to support tumor cell growth through CD40–CD40 ligand (CD40L) interactions." (PMID 33804869, 2021).